IL6 (interleukin 6)
Diseases named in the same sentence as IL6 in open-access papers (continued):
Sharing a sentence is not in itself a finding about the gene and the disease.
Obesity (continued). "Mauer and colleagues demonstrated that inactivation of IL-6R/IL-6 signaling in myeloid cells of experimental animals attenuates obesity-induced inflammation and insulin resistance by promoting M2 macrophage alternative activation." (PMID 37231519, 2023). "Obesity is considered a low-grade chronic inflammatory status with the increased secretion of pro-inflammatory cytokines from adipocytes, including IL-6 and TNFα." (PMID 37185433, 2023). "TNF-alpha and IL-6 are pro-inflammatory cytokines that can be produced by adipose tissue in response to obesity-related stress." (PMID 37629396, 2023). "IL-6 is highly expressed in obesity, and elevated IL-6 levels in circulation are related to insulin resistance." (PMID 37512149, 2023). "Serum concentrations of adipokines, leptin, adiponectin, visfatin and resistin and inflammatory markers associated with low-grade inflammation in obesity, CRP, IL-6, sE-selectin, sVCAM, sPECAM and VEGF, were similar in both groups, regardless of CK-18." (PMID 37189422, 2023). "An increase in the level of IL-6 with the progression of obesity is directly related to an increase in the content of adipose tissue." (PMID 37694871, 2023). "In individuals with obesity, IL-6 and TNF-α have more secretion in the morning instead of the night and are related to BMI and sleep disorder." (PMID 37275639, 2023). "High levels of Deferribacteres are often related to obesity, which is positively linked with the pro-inflammatory factors, IL-6, IL-17A, and TNF-α, causing the aggravation of inflammation in obesity." (PMID 37376017, 2023). "The increase in IL6 expression during exercise also suppresses hyperphagia and reduces obesity-induced hypothalamic inflammation, thereby promoting insulin and leptin sensitivity and re-establishing balances in the control of appetite and energy homeostasis." (PMID 36986146, 2023). "Adipocytokines, such as tumor necrosis factor α (TNF-α) or interleukin (IL)-6, are generally elevated with increasing adiposity and play an important role in the development of metabolic complications in obesity." (PMID 36674952, 2023). "Increased IL6 levels found in obesity possibly serve as an adaptive mechanism in order to limit inflammation and balance metabolic comorbidities." (PMID 36986146, 2023). "Since obesity triggers a chronic low-grade inflammatory response, blood samples from all three dietary intervention groups were analyzed for inflammatory factors IL-6 and TNF-α." (PMID 37601677, 2023). "We next examined if obesity affected the production of psoriasis-related proinflammatory cytokines IL-6 and TNF-α in the serum after imiquimod treatment." (PMID 36982669, 2023). "In obesity, stress, hormones (insulin, catecholamines, glucocorticoids), hypoxia, and inflammation interact and affect IL6 production." (PMID 36986146, 2023). "The chronic low-grade inflammatory environment typical of obesity, in which circulating cytokines, including IL-6, are hyperactivated, further contributes to immunosuppression and disproportionate cytokine activation." (PMID 37686837, 2023). "IL-6 is a biomarker of systemic inflammation, metabolic dysfunction, and obesity, and its level is increased in serum and airways in individuals with asthma." (PMID 37529050, 2023). "Hypoadiponectinemia in obesity is caused by adipocyte hypoxia, oxidative stress, insulin resistance, and increased pro-inflammatory cytokines such as TNF-α and IL-6." (PMID 37104164, 2023). "In conclusion, IL-1β, IL6, IL-10, and IP-10 levels are elevated in adolescents with severe obesity and these cytokines can serve as a tool for the diagnosis of MetS." (PMID 37336969, 2023). "ER stress and inflammation in obesity result in the elevation of pro-inflammatory cytokines, including IL-6 and TNF-α." (PMID 38140341, 2023).
Obesity (continued). "Many of the common secreted upstream regulators we identified, such as TNF, IL-1β, IFN-γ, IL-18, CD40L, IL-6, EGF, TGFβ, and IL-21, were previously reported to be associated with obesity and metabolic dysfunction." (PMID 36880999, 2023). "IL-6 has also been suggested to protect α-cells from apoptosis induced by metabolic stress and promote α-cell mass expansion during obesity as a compensatory response." (PMID 36674557, 2023). "For example, we show increased systemic inflammation in obese female mice housed at TN, aligning with human studies identifying increased serum endotoxin and IL-6 in mothers with obesity." (PMID 38068816, 2023). "Obesity increases pro-inflammatory IL-6 and TNF-α levels and decreases anti-inflammatory hormone adiponectin." (PMID 37229273, 2023). "MCP-1 is stimulated by the presence of IL-1β, TNF-α, IL-8, IL-4, and IL-6, and thus further aids in the macrophage recruitment to adipose tissue seen in obesity." (PMID 37571308, 2023). "In obesity, expanding adipose tissue secretes proinflammatory adipokines, such as interleukin-6 (IL-6) and TNF-a, which can lead to inflammation and metabolic dysfunction associated with obesity." (PMID 37296584, 2023). "Pro-inflammatory adipokines (MCP-1, IL-6, PAI-1), usually stimulated and increased in obesity, are closely associated with pancreatic tumors." (PMID 37176160, 2023). "In animal models of obesity used to explore IL-6 biological functions, a paradoxical role of IL-6 signaling in modulating inflammation and metabolism is reported." (PMID 38136564, 2023). "Inflammatory markers, such as hs-CRP, IL-6, and TNF-α-R2 levels in the blood, were negatively correlated with dietary fibre intake by reducing body weight or limiting obesity-associated systemic inflammation." (PMID 37764817, 2023). "IL-6 suppresses the synthesis of adiponectin and impairs insulin signaling, which together contribute to inflammation in obesity." (PMID 37251328, 2023). "Given that no other studies have examined the associations of other inflammatory markers with quality of life in metabolically unhealthy people with obesity, our findings regarding IL-6 and TNF-α can be considered of significant importance." (PMID 37529617, 2023). "Both diseases are related to obesity via the complex influence of proinflammatory cytokines (IL-6, IL-17, TNF-α) and adipokines, leading to cardiometabolic disturbances." (PMID 37891954, 2023). "The correlation between TNF-α, IL-6, and their involvement in obesity and metabolic disorders is well-established." (PMID 37919772, 2023). "Firstly, six key adipokines known to be deregulated in obesity and related metabolic and vascular complications are described, namely adiponectin, leptin, resistin, IL-6, MCP-1 and PAI-1." (PMID 38136564, 2023). "For example, IL-6 is known to be increased in obesity, shares signaling pathways with leptin, and can have synergistic effects on T cells." (PMID 37276236, 2023). "The release of the inflammatory cytokine IL-6 is stimulated, among others, by oxidative stress and obesity." (PMID 37371951, 2023). "Age and comorbidities—particularly hypertension, obesity, diabetes and chronic heart disease—were found to be independent risk factors linked to in-hospital mortality, while LDH and IL-6 showed a borderline significance." (PMID 36836679, 2023). "Specific inflammatory cytokines are produced in response to increased fat stores during obesity [interleukin-6 (IL-6) and TNF]." (PMID 37534085, 2023). "One of the components of the pathogenesis of obesity is inflammation, and many inflammatory cytokines such as C-reactive protein, IL-6, and TNF-α play a vital role in the disease and are also commonly raised in seborrheic dermatitis patients." (PMID 37503468, 2023). "Circulating IL-6 is elevated in individuals with obesity, and AT is one of the main sources of this inflammatory mediator." (PMID 37239916, 2023).
Obesity (continued). "Mast cells also have an inflammatory phenotype in obesity, characterized by increased expression of IL-6 and CCL2, as well as tryptase and chymase, which are components of mast cell granules." (PMID 37296891, 2023). "The condition of obesity leads to the development of an inflammatory environment in the body, characterized by elevated levels of various markers such as C-reactive protein, interleukin-6, and tumor necrosis factor-α in the bloodstream." (PMID 37109333, 2023). "Systemic low-grade inflammation is a cornerstone in the relationship between obesity and carcinogenesis, a relationship best described by the actions of released adipokines (studied here), interleukin 6 (IL-6) and Tumor Necrosis Factor α (TNF-α)." (PMID 36900364, 2023). "Fifth, since TNF-α and IL-6 are also produced by macrophages in the adipose tissue and muscle, information, such as obesity and physical activity in SZ patients should be included when the patient enters the hospital." (PMID 37937262, 2023). "Higher levels of Interleukin-6 are seen in obesity, with increased secretion from hepatic stellate cells and Kupffer cells within the liver." (PMID 37005953, 2023). "Pro-inflammatory cytokines that are associated with obesity and aging include tumor necrosis factor α (TNF-α), interleukin 6 (IL-6), and C-reactive protein (CRP), which cause peripheral blood mononuclear cells to be in a pro-inflammatory state." (PMID 37372149, 2023). "Several other inflammatory indicators, including IL-1β, IL-6 and C-reactive protein (CRP) are also associated with obesity." (PMID 37241120, 2023). "IL-6 was positively correlated with obesity; however, the role of IL-6 was controversial, as IL-6 disrupted insulin signaling pathways, resulting in insulin resistance." (PMID 37426418, 2023). "IL-1β, TNF-α and IL-6 are inflammatory cytokines correlated with and involved in obesity-related inflammation and insulin resistance, respectively." (PMID 37796781, 2023). "Obesity and metabolic syndrome are pro-inflammatory states characterised by the release of inflammatory mediators such as interleukin 6 (IL-6) and TNF-α." (PMID 37233716, 2023). "Studies carried out in adults with obesity, hyperglycemia, and insulin resistance demonstrate parallel increases in their IL-6 and CRP concentrations with increasing insulin resistance." (PMID 37892418, 2023). "Due to the characteristic of adiponectin/leptin ratio in obesity in general, there is strong possibility that the ratio would also serve as an excellent marker for pancreatic cancer, similar to IL-6/IL-8 ratio, for tracking inflammation for clinical purposes." (PMID 37181043, 2023). "Obesity causes the rise of various inflammatory cytokines and matrix metalloproteinases (MMP) such as interleukin (IL)-1 β, IL-6, MMP-1, MMP-6 and MMP-13." (PMID 38033821, 2023). "Although IL-6 is regarded as a systemic regulator of body weight, lipid metabolism, and glucose uptake, the role of IL-6 in obesity remains controversial." (PMID 37187893, 2023). "In obesity, elevated levels of IL-6 and TNF-α and reduced levels of adiponectin are observed, and the associated chronic inflammation favors the development of cardiometabolic diseases." (PMID 37375693, 2023). "Obesity with visceral fat accumulation, which increases the levels of leptin, TNFα, IL-6 and resistin, and decreases the level of adiponectin, is related to cancer risk and mortality." (PMID 36879265, 2023). "Accordingly, the goal of this narrative review is to summarize the effects of TRE and ADF on body weight and key circulating inflammatory markers, i.e., CRP, TNF-alpha, and IL-6, in adults with overweight and obesity." (PMID 37139450, 2023). "In animal models, during obesity development, IL6 production in adipose tissues is consistently elevated, especially in insulin-resistance adipocytes." (PMID 37298352, 2023).
Obesity (continued). "The additional factors that contribute to the AMPK activation after combined treatment are increased cytokines in these animals, since Il1b, as obesity-related, and Il6, as a muscle energy sensor, contribute to increased AMPK activity." (PMID 37371678, 2023). "Obesity in turn causes a pro-inflammatory state systemically and blood concentrations of CRP, IL-6 and other cytokines have previously been associated with changed (increased) micro-structural MRI metrics of free water." (PMID 37861301, 2023). "In the case of obesity, the amount of proinflammatory cytokines tumor necrosis factor alpha, interleukin 1, and interleukin 6 produced from adipocytes increases." (PMID 37909201, 2023). "It is well-documented that IL-6 secretion is upregulated in obesity, with positive relationships being found between adipose tissue mass, adipocyte cell size, and IL-6 secretion." (PMID 36766750, 2023). "Conversely, elevated levels of circulating IL-6 have been observed in individuals with T2D, obesity, and insulin resistance." (PMID 37755259, 2023). "Individuals with both obesity and vitamin D insufficiency exhibit elevated levels of proinflammatory cytokines, such as IL-6 and TNFα (tumor necrosis factor α)." (PMID 38276294, 2023). "The pro-inflammatory ATMs are one of the key cell types responsible to produce pro-inflammatory cytokines such as TNF-α, IL-1β, and IL-6, which contribute to obesity-related adipose tissue inflammation." (PMID 37153549, 2023). "Further evidence supports the role of obesity-induced inflammatory responses (IL-6, TNF-α, and leptin) in tamoxifen-acquired BC resistance." (PMID 36880535, 2023). "Our previous work showed that young adults with obesity exhibited a comparable concentrations of IL-6 to acute aerobic exercise when compared to normal-weight counterparts." (PMID 37372149, 2023). "We recently reported that liraglutide treatment transiently induced interleukin-6 (IL6) in circulation and AT beiging in prediabetic patients and that this effect was recapitulated in the mouse model of obesity." (PMID 38201269, 2023). "Recent studies have indicated that elevated serum levels of IL-6 and IL-17 in mice with diet-induced obesity (DIO) promoted Th17 cell differentiation." (PMID 36982669, 2023). "Pro-inflammatory cytokines such as TNF-α, IL-1β, and IL-6, which are mainly produced by immune cells and adipocytes, play a vital role in the pathogenesis of obesity and OA." (PMID 37703108, 2023). "Obesity is characterized by a chronic state of low-grade inflammation in which circulating levels of several inflammatory markers, such as IL-6 and MCP-1, and IL-8 are significantly higher compared to the nonobese." (PMID 36674952, 2023). "Compared with allergic asthma, IL-6 levels are also influenced by viral infection, obesity and increased intrinsic asthma." (PMID 37492220, 2023). "Studies in the general population have shown a positive correlation between elevated IL-6, obesity, insulin resistance, and hyperandrogenism, which are all comorbidities associated with PCOS." (PMID 37195871, 2023). "Specifically, in obesity, dysfunctional adipose tissue predominantly secretes proinflammatory adipokines (e.g., leptin, resistin, interleukin-6 (IL-6), and tumor necrosis factor-α (TNF-α)) in detriment of the anti-inflammatory ones (e.g., adiponectin)." (PMID 37432255, 2023). "Chronic inflammation caused by obesity leads to increased secretion of tumor necrosis factor-α (TNF-α), IL-6, IL-18, and other Th1 cytokines that can also inhibit adiponectin." (PMID 37266440, 2023). "The IL-6 gene in lipopolysaccharide (LPS)-induced adipose stem cells treats obesity-related inflammation and chronic disease." (PMID 37835263, 2023). "Considerable researches have proved that PQQ has a positive effect on inflammatory diseases such as obesity, diabetes, and sepsis via the mediation of pro-inflammatory cytokine such as IL-6, IL-1β and TNF-α." (PMID 37935689, 2023).
Obesity (continued). "Obesity and age-related increases in inflammatory cytokines (e.g. TNF-α, IL-6, and CRP) cause exacerbated danger-associated molecular patterns and immunosenescence, thereby increasing morbidity and mortality." (PMID 37372149, 2023). "Obesity predisposes to a chronic inflammatory state which is accompanied by higher levels of pro-inflammatory cytokines such as RANTES, TNF-α, IL-6 and IL-18." (PMID 36771387, 2023). "Obesity causally increases gastric cancer, likely mediated by persistent AKT1/IL-6/TNF upregulation." (PMID 37954072, 2023). "Further integrated bioinformatics and meta-analysis of multi-omics data and clinical evidence points to interconnected inflammatory and immune dysfunction centered around AKT1, IL-6, and TNF as key mechanisms linking obesity to elevated gastric cancer risk." (PMID 37954072, 2023). "It has been shown that obesity-induced low-grade inflammation (raised IL-1, IL-6, and TNF-alfa levels) activates stress kinases, including IKK, JNK, and p38 MAPK, in muscle and fat cells." (PMID 37764744, 2023). "TNF-α, primarily secreted by adipose tissue, exhibits elevated gene and protein expression in the presence of obesity, whereas only 30% of IL-6 production originates from adipose tissue." (PMID 37919772, 2023). "The secretion of inflammatory cytokines such as tumor necrosis factor-α (TNF-α) and interleukin 6 (IL-6) by adipocytes is increased in obesity-induced adipose tissue inflammation." (PMID 37892415, 2023). "Inflammatory markers, including C-reactive protein, interleukin-6, and tumor necrosis factor, are positively related to obesity and the aggravation of insulin resistance." (PMID 36803382, 2023). "The administration of HRCHFC diet for 8 weeks initiated the development of obesity and low-grade chronic inflammation mediated by the liberation of pro-inflammatory cytokines like IL-6 and TNF-α." (PMID 37033655, 2023). "Upregulation of TNF-α and IL-6 promoted hepatic steatosis and inflammation in a mouse obesity model." (PMID 38313077, 2023). "Previous studies have demonstrated that obesity is correlated with the enhanced secretion of inflammatory cytokines, including IL-6, IL-1β, and TNF-α." (PMID 38035300, 2023). "Direct mechanisms tying obesity-driven increases in adipose tissue to tumor cell proliferation and survival through secretion of cytokines such as leptin and IL-6, or to myeloma cell drug resistance are being unveiled." (PMID 36909335, 2023). "In children, IL-6 concentrations were also higher in those with obesity than in those with a normal BMI, especially in preadolescence." (PMID 37892418, 2023). "IL6 is a known regulator of adipose homeostasis in obesity and is high secreted from adipose tissue." (PMID 36647068, 2023). "Reductions in TNF α and IL-6 levels were also observed in a group of patients with severe obesity undergoing bariatric surgery." (PMID 38276294, 2023). "This positive feedback loop of IL-6 activity can be initiated by a variety of stimuli including infection, obesity, and stressors further promoting inflammation." (PMID 37049389, 2023). "Elevated levels of circulating IL-6 and CRP, which is stimulated by IL-6 in the liver, are observed in obesity and serve as predictive markers for type 2 diabetes in predisposed individuals." (PMID 38004353, 2023). "CRP, IL-6 and adiponectin levels were similar to other surveys in Greek metabolically unhealthy cohorts with obesity." (PMID 37529617, 2023). "Reductions in body weight and visceral fat mass by diet and bariatric surgery have been shown to reduce circulating levels of IL-6 in individuals with obesity, though findings are variable." (PMID 37139450, 2023). "Obesity induces various metabolic dysfunctions and inflammatory processes that increase insulin, insulin-like growth factor, leptin, and interleukin-6, while decreasing adiponectin." (PMID 38013342, 2023). "The main adipokines associated with development of obesity are leptin, adiponectin, resistin, TNF-alpha, and IL-6." (PMID 37629396, 2023).